HRG (histidine rich glycoprotein)
Diseases named in the same sentence as HRG in open-access papers (continued):
Sharing a sentence is not in itself a finding about the gene and the disease.
tumor (continued). "First, we validated that HRG was downregulated in a transformation model by western blot analysis and quantitative real-time PCR (qPCR), as well as in 31 paired human HCC tissues and tumor surrounding liver tissues by western blotting." (PMID 26336134, 2015). "From the field of angiogenesis it has been discovered that a histidine-rich glycoprotein (HRG) inhibits tumor growth and metastasis not only because it regulates tumor vessel abnormalization and has anti-angiogenic properties but because of its capacity to skew M2 macrophages into M1." (PMID 26561829, 2015). "Also, when using the minimal active antiangiogenic domain of HRG (HRGP330, a 35 amino acid peptide) to treat subcutaneous human pancreatic adenocarcinomas in SCID mice tumor vascularization was significantly reduced." (PMID 20046875, 2009). "Interestingly, the GEPIA analysis also revealed that HRG expression was significantly higher in the non-tumoral areas compared with the tumor tissue." (PMID 38469298, 2024). "Without host derived PlGF, HRG does not further suppress tumor growth." (PMID 37626639, 2023). "Furthermore, expression data from the TCGA, GSE14520, and GSE6764 datasets showed that HRG was dramatically lower in tumor tissues than in non-tumorous counterparts." (PMID 32929358, 2020). "In the present study we address how lack of HRG affects tumor growth." (PMID 21264222, 2011). "Parallel macro-autoradiography in which 125I-mHRG was incubated directly on spleen and tumor sections in the absence and presence of a 100-fold molar excess of unlabeled HRG, showed that binding of 125I-mHRG was efficiently blocked by unlabeled HRG (data not shown)." (PMID 25243896, 2014). "We also noted that HRG+/− mice have an intermediary tumor volume (data not shown) between HRG+/+ and HRG−/− mice, which may be related to the fact that mice with one inactivated HRG allele have approximately half the serum concentration of HRG-protein compared to HRG sufficient mice." (PMID 21264222, 2011). "For in vitro receptor activation, the medium was supplemented with a mixture of the growth factors EGF, HRG, HGF and IGF to compensate for the absence of tumor–stroma interactions." (PMID 27578890, 2016).
cancer (28 papers, 2009 to 2026). A tumor composed of atypical neoplastic, often pleomorphic cells that invade other tissues. "Histidine-rich glycoprotein (HRG) is a 75 kDa abundant plasma protein produced by hepatocytes and implicated in cancer immune responsiveness." (PMID 36078092, 2022). "The underlying mechanism of repressed expression of HRG in cancer cells may be partly attributed to the activation of NF‐κB signalling." (PMID 37254661, 2023). "In cancer patients, HRG fusion is linked to a poor prognosis." (PMID 36727079, 2022). "Aberrant expression of HRG has been implicated in several cancers." (PMID 33553172, 2020). "Histidine-rich glycoprotein (HRG) has been detected in plasma and has been suggested as a potential prognostic and diagnostic biomarker in cancer." (PMID 40470116, 2025). "At present, only few studies have investigated HRG’s role in cancer development and, to our knowledge, its role in MASH-related hepatocarcinogenesis has never been addressed." (PMID 38469298, 2024). "Among them, TIMP1, LGALS3BP, A2M, AHSG, FN1, HRG, and ITIH4 have been associated with cancer, while CF I, C2, and C4A, have been related to complement activity." (PMID 37685286, 2023). "Immunofluorescence staining experiments for lung metastases also confirmed the inhibitory effect of HRG on neutrophils in lung metastases, and we observed a positive correlation between the number of Ki67+ cancer cells and neutrophils." (PMID 37254661, 2023). "Consistently, HRG knockdown cancer cells and cancer cells in KO‐HRG mice seeding increased, indicating that HRG plays a critical role in the early metastatic stage." (PMID 37254661, 2023). "By flow cytometry assays, we found that HRG overexpression cancer cells inhibited CD11b+Ly6G+ neutrophils, while HRG knockdown cancer cells and KO‐HRG mice enhanced the percentage of CD11b+Ly6G+ neutrophils rather than other immune cells." (PMID 37254661, 2023). "Immunofluorescence staining of lung tissue further confirmed that neutrophils around HRG overexpression cancer cells increased, and neutrophils around HRG knockdown cancer cells and cancer cells in KO‐HRG mice decreased." (PMID 37254661, 2023). "There is little information about the molecular mechanism underlying the transcriptional regulation of HRG in hepatocytes in the liver; therefore, our investigation into the downregulation of HRG under cancer-mediated inflammation is ongoing." (PMID 36142212, 2022). "The abundant hepatocyte‐expressed plasma protein histidine‐rich glycoprotein (HRG) enhances antitumor immunity by polarizing inflammatory and immune cells in several mouse models, however, the clinical relevance of HRG in human cancer is poorly explored." (PMID 35847718, 2020). "There is evidence for an active involvement of HRG in cancer largely by displaying both pro- and antiangiogenic properties." (PMID 30944671, 2019). "Existing evidence indicates that HRG represents an adaptor protein with the potential to modulate immune, vascular, and coagulation systems, which are involved in cancer development." (PMID 30944671, 2019). "In cancer, histidine-rich glycoprotein (a host-produced protein deposited in the stroma) was shown to induce TAM reprogramming from M2 to M1, resulting in vascular normalization and improved response to chemotherapy." (PMID 28670313, 2017). "Collectively, these data suggested that HRG-β1 induced cancer cell migration and invasion through induction of EMT via PI3k/Akt-phospho-Smad2-Snail signaling pathway." (PMID 23937725, 2013). "Furthermore, HRG has been proposed to suppress HCC cell growth by inducing cancer cell apoptosis, possibly though an interaction of TNFα with its type 1 receptor." (PMID 38469298, 2024). "In addition, we depleted neutrophils in mice with anti‐Ly6G antibody and found that the lung metastatic regulation effect of HRG on cancer cells was eliminated." (PMID 37254661, 2023).
cancer (continued). "We further explored the NETs after lung tumorigenesis and found that NETs in lung metastases overexpressed with HRG decreased, while NETs in lung metastases with HRG knockdown and KO‐HRG mice increased, while Ki67+ cancer cells were positively correlated with NETs." (PMID 37254661, 2023). "The mechanism can partly explain that HRG down‐regulates in cancer cells." (PMID 37254661, 2023). "In addition, HRG activates natural killer (NK) cell–cancer cell cytotoxicity through the downregulation of programmed-death-1 (PD-1), a cancer immune tolerance mediator, on the NK cell surface." (PMID 36142212, 2022). "The notable anti-cancer effect of HRG in vivo leads to our last point of discussion." (PMID 36142212, 2022). "These facts indicate the potential of HRG to be a new target for cancer immunotherapy." (PMID 31143450, 2019). "Previously, we reported that HRG immunodetection is decreased in a range of human cancers." (PMID 25243896, 2014). "The HRG-β1-induced expressions of Snail, vimentin, and fibronectin, and nuclear colocalization of phospho-Smad2 and Snail were inhibited by pretreatment with a PI3k inhibitor, LY294002, or two phospho-Smad2 inhibitors, PD169316 or SB203580 and cancer cell migration by HRG-β1 was inhibited." (PMID 23937725, 2013). "These compounds have shown potential for treatment of cancer suggesting that targeting CD36 or HRG could present effective alternative approaches to enhance or inhibit TSR action." (PMID 22808089, 2012). "The up-regulation of αvβ3 integrin and low expression of HRG/NRG1 in cancer cells could be a novel molecular marker of chemosensitivity." (PMID 19775429, 2009). "In the same study, the authors provide evidence that macrophages are a direct HRG target, concluding that HRG deletion may favor cancer cell growth and metastasis by modulating macrophage phenotypes with the stimulation of pro-angiogenic and immunosuppressive functions." (PMID 38469298, 2024). "To explore whether HRG regulates neutrophil NETosis, we explored the effect of HRG on lung NETs in the early metastasis stage and found that NETs around HRG overexpressed cancer cells decreased, while NETs around HRG knockdown cancer cells and cancer cells in KO‐HRG mice increased." (PMID 37254661, 2023). "Collectively, those interactions could play significant roles in HRG-mediated anti-cancer effects." (PMID 36142212, 2022). "Thus, it seems reasonable to speculate that HRG may also function to block cancer activation by regulating young neutrophils." (PMID 36142212, 2022). "Conversely, HRG knockdown by short hairpin RNA in LM3, enhanced lung metastases of cancer cells and shortened the survival of mice." (PMID 37254661, 2023). "HRG overexpression in SKHEP1, reduced lung metastases of cancer cells and prolonged the survival of mice." (PMID 37254661, 2023). "Consistently, HRG overexpressed cancer cell CM reduced the MPO activity and the number of neutrophils and the MPO activity of neutrophils treated with HRG knockdown cancer cell CM was higher." (PMID 37254661, 2023). "Several upregulated genes (LRP1, SERPINA1, HRG, ILK, CAV1, and LAMA4) identified in our study are involved in GEM resistance in human cancer 23-28." (PMID 35281857, 2022). "In this study, we identified HRG as a novel plasma protein that binds directly to and inhibits the heterodimer S100A8/A9, effectively preventing S100A8/A9-mediated organotropic cancer metastasis." (PMID 36142212, 2022). "Considering the clinical data showing a reciprocal relationship between HRG and S100A8/A9, their balance in cancer patients is one of the few potent determinants of a shift in cancer metastasis to a highly aggressive state." (PMID 36142212, 2022). "HRG expression in HCC is suppressed by DNA methylation or via feedback inhibition by NF-κB, thereby supporting cancer cells to survive and thrive (Graphical abstract)." (PMID 32929358, 2020).
cancer (continued). "CRTAC1, HRG, and IL1R2 are not cancer‐specific biomarkers, but they are broadly associated with various diseases." (PMID 40517318, 2025). "HRG overexpression or knockdown of cancer cells did not alter the attraction effect of CM on neutrophils." (PMID 37254661, 2023). "Consistently, we performed RNA sequencing and differentially expressed gene enrichment analysis on human neutrophils treated with CM of HRG overexpressed cancer cells, and the results showed that the MAPK signalling pathway of neutrophils treated with HRG overexpressed cancer cells CM was altered." (PMID 37254661, 2023). "Given the multiple molecules that interact with HRG, HRG-mediated cancer prevention in vivo would not be attributable to the prevention of S100A8/A9 activities alone." (PMID 36142212, 2022). "Surprisingly, however, there have been no reports on HRG’s interaction with S100A8/A9 or on the relevance of HRG to S100A8/A9-mediated cancer biology." (PMID 36142212, 2022). "Increased sensitivity of HCC cells to 5-fluorouracil-induced apoptosis was found with HRG overexpression which enhanced TNFR1 protein stability in the present study, pointing out a possibility that ways to upregulate HRG expression may become an adjuvant approach for cancer treatment." (PMID 32929358, 2020). "The detailed mechanisms of action of CRTAC1, HRG, and IL1R2 in cancer progression are not yet fully established." (PMID 40517318, 2025).
infection (5 papers, 2008 to 2017). The state of being infected such as from the introduction of a foreign agent such as serum, vaccine, antigenic substance or organism. "Taken together, and considering the role of HRG in innate immunity, it should be of interest to study potential associations between functional inactivation(s) or deficiencies of HRG as well as genetically determined differences, in relation to the occurrence of infections." (PMID 18797515, 2008). "The cells were infected with RCAS viruses expressing HRG, PDGFB-HA or eGFP (control) and subsequently stained for GFP, HRG and HA to determine infection efficiency." (PMID 20046875, 2009). "In mouse infection models, HRG was protective against systemic infection by Candida, indicating a novel antifungal role of HRG in innate immunity." (PMID 18797515, 2008). "The expression of 38 proteins in the acute-phase response signalling pathway changed over the course of the infection, with maximum upregulation observed from as early as 42 h, e.g. for HRG and alpha-2-macroglobulin, to as late as 312 h for complement C1 subcomponent and retinol-binding protein." (PMID 27412694, 2016). "The capacity of HRG to kill Candida at these pH levels and the corresponding increase in salt-resistance at low pH suggest that HRG could target infection foci, resulting in a physiologically relevant concentration and localization of antifungal activity." (PMID 18797515, 2008).
bacterial infection (2 papers, 2014 to 2022). "Additionally, HRG could be of particular importance in bacterial infection due to its ability to bind these pathogens." (PMID 36430174, 2022).
HRG also shares sentences with these, for which no sentence is quoted: ventilator-associated pneumonia (3 papers); kidney cancer (2); lung fibrosis (2); abdominal aortic aneurysm (1); acute pancreatitis (1); asthma (1); chronic hepatitis C (1); coagulopathies (1); fibrosarcoma (1); flu (1); Infertility (1); Lewis lung carcinoma (1); liver cirrhosis (1); liver fibrosis (1); malignant glioma (1); mantle cell lymphoma (1); myopia (1); pancreatic ductal adenocarcinoma (1); post-thrombotic syndrome (1); pulmonary disease (1); renal carcinoma (1); renal disease (1); systemic inflammatory response syndrome (1); systemic lupus erythematosus (1).